SIRT6 (sirtuin 6)
Diseases named in the same sentence as SIRT6 in open-access papers (continued):
Sharing a sentence is not in itself a finding about the gene and the disease.
melanoma (27 papers, 2016 to 2026). A malignant, usually aggressive tumor composed of atypical, neoplastic melanocytes. "Loss-of-function SIRT6 mutations from melanoma patients compromise DNA repair capacity, destabilize the genome and contribute to tumorigenesis." (PMID 41463311, 2025). "Intriguingly, histone deacetylase SIRT6 haploinsufficiency promoted melanoma MAPKi resistance, while complete loss conferred sensitivity due to induction of the DNA damage response." (PMID 36497341, 2022). "Because muscle atrophy is a major hallmark of cancer‐associated weight loss, we challenged the muscle‐specific SIRT6 over‐expressing (Sk.T6Tg) mice with subcutaneous injection of B16F10 melanoma cells on the flank of the animal." (PMID 34212132, 2021). "In our study, we uncovered a new role for the NAD-dependent chromatin-associated deacetylase SIRT6 in melanoma drug resistance." (PMID 32042336, 2020). "We then counted the nonsynonymous mutation numbers of the TCGA and ICGC melanoma patients and found that among them, four mutations in SIRT6, P27S, H50Y, R150* and G134W, correlated with high mutation rates across the genome." (PMID 32789493, 2020). "To determine if the observed anti-proliferative response of SIRT6 knockdown in melanoma cells was associated with a dysregulation in cell cycle, we performed a cell cycle distribution analysis by flow cytometry." (PMID 29234488, 2017). "As autophagy is important in melanoma and is associated with SIRT6, we used a qPCR array to study SIRT6 knockdown in A375 cells." (PMID 29234488, 2017). "In addition, we found that RNA interference-mediated knockdown of SIRT6 reduces cellular growth, viability, and colony formation in A375 and Hs 294T melanoma cells, further underlining the potential pro-proliferative function of SIRT6 in melanoma." (PMID 29234488, 2017). "In addition, we characterized several SIRT6 mutations derived from melanoma patients." (PMID 32789493, 2020). "Moreover, through data mining, we identified 8 mutations in SIRT6 in melanoma patients." (PMID 32789493, 2020). "Autophagy is regulated by SIRT6 in BRAF-mutant melanoma dependent on the stage of the melanoma cells, and SIRT6 expression correlated with the expression of the autophagy factors LC3 and p62." (PMID 39935431, 2025). "SIRT6 was downregulated in primary melanoma cells but upregulated in cells from metastatic cell lines." (PMID 39935431, 2025). "SIRT6 acts as an oncogene, inducing G1‐phase arrest and senescence‐like phenotypes in melanoma cells." (PMID 39494561, 2024). "In melanoma, breast, lung, pancreatic, liver, prostate, colon, ovarian, and blood cancers, SIRT6 has contradictory roles as either oncogene or tumor suppresser at different stages of the cancer or in different tumor cell lines." (PMID 35463332, 2022). "Mechanistically, autophagy aids the degradation of toxic protein at initial stages, but also reduces cancer cell susceptibility to stress and promotes the development of established tumors, hence explaining SIRT6 dual role in melanoma." (PMID 33800266, 2021). "FoxO3a was recently found to regulate aerobic glycolysis by modulating the expression of sirtuin 6 (SIRT6), which is recognized as a key regulator of cellular metabolism in melanoma." (PMID 34418600, 2021). "It is suggested that FOXO3a expression is positively correlated with SIRT6 expression and that the FOXO3a-SIRT6 regulatory axis inhibits glucose metabolism and tumor cell proliferation in melanoma." (PMID 34418600, 2021). "On the other hand, in human melanoma cells SIRT6 knockdown induced G1-phase arrest and senescence-like phenotypes." (PMID 33684691, 2021). "Using, a combination of transcriptomic, epigenomic and proteomic analyses we demonstrated that haploinsufficiency of SIRT6 in BRAF-mutant melanoma cells decreases sensitivity to MAPKi independently of the ERK signaling pathway." (PMID 32042336, 2020).
melanoma (continued). "SIRT1, SIRT6 and SPHK1 induced EMT by up-regulating autophagy-linked lysosomal degradation of E-cadherin in melanoma and hepatocellular cells via Beclin 1-E-cadherin cascade respectively." (PMID 33425768, 2020). "We investigated the ChIP-sequence dataset GSE102813 that analyzed SIRT6 depletion in BRAFV600E melanoma cells." (PMID 32983963, 2020). "We investigated the ChIP-sequence dataset GSE102813, which studied SIRT6 depletion in BRAFV600E melanoma cells." (PMID 32983963, 2020). "Here, using a CRISPR–Cas9 screen targeting chromatin regulators, we discover that haploinsufficiency of the histone deacetylase SIRT6 allows melanoma cell persistence in the presence of MAPKi." (PMID 30143629, 2018). "Combining a clinically applicable IGF-1Ri with BRAFi overcomes resistance of SIRT6 haploinsufficient melanoma cells in vitro and in vivo." (PMID 30143629, 2018). "Collectively, these in vitro and in vivo results suggest that partial suppression of SIRT6 confers BRAFV600E melanoma cells the ability to persist in the presence of MAPKi." (PMID 30143629, 2018). "Here, the authors develop a CRISPR-Cas9 screen targeting epigenetic regulators and discover that SIRT6 haploinsufficiency induces BRAFV600E melanoma cell resistance to MAPK inhibitors via IGF signalling." (PMID 30143629, 2018). "Knockdown of SIRT6 in several BRAFV600E melanoma cell lines and an STC exhibited resistance to MAPKi." (PMID 30143629, 2018). "Further, using a tissue microarray coupled with quantitative Vectra analysis, we demonstrated significant SIRT6 overexpression in human melanoma tissues." (PMID 29234488, 2017). "We found that compared to NHEM, most of the melanoma cell lines exhibited significantly higher expression of SIRT6 protein and mRNA as assessed by immunoblot and RT-qPCR analyses, respectively." (PMID 29234488, 2017). "Lentiviral short hairpin RNA-mediated knockdown of SIRT6 in A375 and Hs 294T human melanoma cells significantly decreased cell growth, viability, and colony formation, induced G1-phase arrest and increased senescence-associated beta-galactosidase staining." (PMID 29234488, 2017). "Because autophagy and senescence are believed to be functionally intertwined processes, we next wanted to assess the effects of SIRT6 knockdown on autophagy-related pathways in A375 melanoma cells." (PMID 29234488, 2017). "We found that SIRT6 knockdown resulted in an enhanced accumulation of cells in G0/G1 phase in both A375 and Hs 294T human melanoma cell lines." (PMID 29234488, 2017). "Next, we assessed the effects of SIRT6 knockdown on the proliferative potential of melanoma cells using the Promega RealTime-Glo MT Cell Viability Assay and the trypan blue exclusion assay." (PMID 29234488, 2017). "Our study focused on melanocytic cells and we found strong evidences supporting the pro-proliferative function of SIRT6 in melanoma." (PMID 29234488, 2017). "This differential expression of SIRT6 in melanoma encouraged us to further explore its role in melanoma." (PMID 29234488, 2017). "Our data demonstrated that SIRT6 knockdown significantly decreased cell growth and viability in both of the melanoma cell lines tested." (PMID 29234488, 2017). "Overall, our study provides strong evidence suggesting a tumor promoter function of SIRT6 in melanoma, warranting future detailed investigations into the role, mechanism and therapeutic targetability of SIRT6 in melanoma." (PMID 29234488, 2017). "As an initial assessment to understand the functional significance of SIRT6 in melanoma, we employed lentiviral-mediated transient transfection of short hairpin RNA (shRNA) to knockdown the SIRT6 gene expression in A375 and Hs 294T cells." (PMID 29234488, 2017). "SIRT6 knockdown resulted in a marked decrease in colony formation abilities of A375 and Hs 294T melanoma cells, suggesting that knockdown of SIRT6 in melanoma cells results in markedly diminished long-term proliferative potential." (PMID 29234488, 2017).
melanoma (continued). "In an effort to uncover the mechanism behind the anti-proliferative effects shown by the SIRT6 knockdown in melanoma we performed an autophagy PCR array." (PMID 29234488, 2017). "Our data demonstrated that SIRT6 is upregulated, both at mRNA and protein levels, in melanoma cell lines as well as clinical tissue samples of human melanoma." (PMID 29234488, 2017). "Employing a panel of human melanoma cells and normal human melanocytes, we found significant SIRT6 mRNA and protein upregulation in melanoma cells." (PMID 29234488, 2017). "SIRT6 knockdown was found to cause a marked decrease in the protein levels of LC3 II (autophagy related form of LC3), ATG3, ATG7, SQSTM1 and BECN in melanoma cells." (PMID 29234488, 2017). "Our results demonstrate that SIRT6 knockdown significantly alters genes and pathways related to autophagy in melanoma cells both at mRNA and protein levels." (PMID 29234488, 2017). "By contrast, SIRT6 appears to have tumor-suppressive functions in melanoma." (PMID 41463311, 2025). "The FOXO3a-SIRT6 axis represses glycolysis, thereby restraining melanoma growth." (PMID 41463311, 2025). "High expression of SIRT6 in CSCC tissues is associated with the location of the cancer tissue in sun-exposed areas and Broders' grade, but not with gender, age, tumor diameter, etc., consistent with findings in melanoma and non-small cell lung cancer." (PMID 38548549, 2024). "Therefore, resistance to BRAF inhibitors in SIRT6-haploinsufficient melanoma cells can be relieved by combinatory application of a clinically available IGF-1R inhibitor." (PMID 35372044, 2022). "However, in the metastatic stage of melanoma, the expression of SIRT6 increases (possibly induced by FOXO3a) and promotes the development of melanoma in an autophagy-dependent manner by inhibiting IGF-AKT signaling." (PMID 35463332, 2022). "The expression of SIRT6 is decreased in primary melanoma compared with melanocytic nevus." (PMID 35463332, 2022). "Conversely, SIRT6 depletion increases the sensitivity of melanoma to MAPK inhibition (MAPKi)." (PMID 35915188, 2022). "In melanoma, SIRT6 has been shown to act as both a tumor suppressor and promoter." (PMID 33800266, 2021). "FOXO3a-SIRT6 regulatory axis inhibits glucose metabolism and tumor cell proliferation in melanoma." (PMID 34418600, 2021). "Notably, another study indicated that SIRT6 has a dichotomous effect in melanoma, suppressing the growth of primary melanoma while promoting the development of metastatic melanoma both in vitro and in vivo." (PMID 33800266, 2021). "Insulin supplementation has been demonstrated to slow tumour progression in mice carrying B16F10 melanoma, suggesting that reduced tumour growth seen in our SIRT6 over‐expressing mice could be attributed partly to upregulation of insulin levels in these mice." (PMID 34212132, 2021). "Based on previous studies showing direct binding between FOXO3a and the Sirt6 promoter in melanoma, we assessed whether FOXO3a directly controls Sirt6 levels." (PMID 34122724, 2021). "Considering SIRT6 is a member of the Class III histone deacetylases (HDAC) that have been demonstrated inhibited H3K56ac We consulted the CHIP-sequence datasets GSE102813 which studied SIRT6 depletion in BRAFV600E melanoma cells." (PMID 33436551, 2021). "Similar to SIRT1 and SIRT3, SIRT6 has been shown to possess a pro-proliferative role in melanoma." (PMID 33178616, 2020). "However, recent studies from our lab supported by another study by Wang and colleagues have suggested the pro-proliferative role of SIRT6 in melanoma as well." (PMID 33178616, 2020). "In addition, depleting SIRT6 using siRNA in A875 cells, a melanoma cell line, also led to a significant reduction in NER." (PMID 32789493, 2020).
melanoma (continued). "Together, these data suggest additional functions for SIRT6 to explore in melanoma biology, in which we could consider SIRT6 “complete” depletion as a novel strategy in melanoma pathogenesis to enhance their sensitivity to current targeted MAPK therapies." (PMID 32042336, 2020). "Together, these data indicate that SIRT6 haploinsufficiency allows BRAFV600E melanoma cells to survive in the presence of MAPKi by increasing IGFBP2 expression, which in turn activates IGF-1R/IR and downstream AKT signaling, that can be blocked by IGF-1R/IR inhibition." (PMID 30143629, 2018). "To evaluate whether SIRT6 and IGFBP2 levels anti-correlate in human melanoma tissues, we performed SIRT6 IHC on 21 BRAFV600E/K melanomas stained for IGFBP2, and observed a statistically significant inverse correlation (Spearman’s r = −0.462; P = 0.035)." (PMID 30143629, 2018). "Overall, these data suggest that H3K56ac is the primary target of SIRT6 in the context of melanoma." (PMID 30143629, 2018). "Interestingly, our data demonstrated that SIRT6 knockdown induces senescence in melanoma cells as evident by morphological changes (characterized by multinucleated phenotype), as well as increased SA-β-Gal staining." (PMID 29234488, 2017). "Indeed, future studies are required to carefully study the role of SIRT6 and autophagy in early versus late melanomas." (PMID 29234488, 2017). "However, GAA and ATG10 protein levels were found to be increased, following SIRT6 knockdown in melanoma cells." (PMID 29234488, 2017). "This study was undertaken to determine the role of the sirtuin SIRT6 in melanoma." (PMID 29234488, 2017). "This study was undertaken to determine the role and functional significance of SIRT6 in melanoma." (PMID 29234488, 2017). "As the first step of our investigation into understanding the role of SIRT6 in melanoma, we determined the expression profile of SIRT6 in normal human epidermal melanocytes (NHEM) and a panel of human melanoma cell lines (A375, Hs 294T, G361, SK-MEL-2, SK-MEL-28, WM35, WM115 and 451Lu)." (PMID 29234488, 2017). "Next, to determine the clinical significance of SIRT6 in melanoma, we assessed the expression pattern of SIRT6 in human tissues using a human melanoma tissue microarray (TMA), containing a total of 62 cases of malignant melanoma, 20 metastatic malignant melanoma and 18 nevus tissues." (PMID 29234488, 2017). "Our data suggests that increased SIRT6 expression may contribute to melanoma development and/or progression, potentially via senescence-and autophagy-related pathways." (PMID 29234488, 2017). "The objective of this study was to determine the role of the nuclear sirtuin SIRT6 in melanoma." (PMID 29234488, 2017). "Based on our data, it appears that SIRT6 positively regulates autophagy in melanoma cells." (PMID 29234488, 2017). "Recently, SIRT6 mutations were found in several tumor types such as non-small-cell lung cancer, renal clear cell carcinoma, cervical carcinoma, and melanoma." (PMID 27824900, 2016). "Thus, incorporating a clinically suitable IGF-1Ri with BRAFi could pave the way for promoting the sensitivity of SIRT6 haploinsufficient melanoma cells." (PMID 33768092, 2021). "Moreover, we confirmed that SIRT6 interacted with DDB2 in the melanoma cell line A875." (PMID 32789493, 2020). "However, puzzlingly, the G134W mutation in SIRT6 was also associated with high mutation rates in the melanoma patients, but it did not abolish the stimulatory effect of SIRT6 on NER in HCA2-hTERT cells." (PMID 32789493, 2020). "Moreover, metastatic samples were found to have more SIRT6 than primary malignant melanoma samples." (PMID 29234488, 2017). "Here, through an unbiased screening approach, we identified SIRT6-mediated transcriptional regulation of IGFBP2, and consequent activation of IGF-1R/AKT, to play a role in melanoma MAPKi resistance." (PMID 30143629, 2018).
melanoma (continued). "Through integrated transcriptomic, proteomic, and epigenomic analyses, we discover that SIRT6 haploinsufficiency increases IGFBP2 expression and promotes melanoma cell survival through the activation of IGF-1R/AKT signaling." (PMID 30143629, 2018). "SIRT6 haploinsufficiency but not complete SIRT6 loss induced IGFBP2 expression followed by IGF-1R and AKT signaling activation in BRAFV600E melanoma cells, leading to MAPK inhibitor resistance." (PMID 39935431, 2025). "SIRT6 can mediate the transcriptional regulation of IGFBP2 and therefore activate IGF-1R/AKT, which promotes the development of MAPK inhibitor resistance in melanoma." (PMID 35915188, 2022). "Moreover, analysis of TCGA data for primary melanomas revealed that 20% display high SIRT6 mRNA, which anti-correlates with IGFBP2 (via RPPA), suggesting a repressive role of SIRT6 on IGFBP2 expression in melanoma." (PMID 30143629, 2018). "We found that SIRT6 haploinsufficiency in BRAFV600E melanoma cells decreases sensitivity to MAPKi, independent of the ERK signaling pathway." (PMID 30143629, 2018). "Together, these data suggest that SIRT6 haploinsufficiency in BRAFV600E melanoma cells decreases sensitivity to MAPKi independent of ERK signaling." (PMID 30143629, 2018). "We identify SIRT6 as a regulator of resistance to the clinically relevant BRAF inhibitor (BRAFi), dabrafenib, or combination dabrafenib + trametinib (MEK inhibitor, MEKi) in BRAFV600E melanoma." (PMID 30143629, 2018). "In contrast to SIRT6 haploinsufficient melanoma cells, melanoma cells lacking SIRT6 undergo chromatin reorganization reflected by increased open chromatin and H3K56ac at these nucleosome-depleted sites." (PMID 30143629, 2018). "However, in BRAFV600E melanoma cells, SIRT6 haploinsufficiency induced resistance of melanoma cells to mitogen-activated protein kinase (MAPK) inhibitors by activating IGF signaling, suggesting an anti-tumor effect of SIRT6." (PMID 35463332, 2022). "Employing CRISPRCas9 screen targeting chromatin regulators illuminate that SIRT6 haploinsufficiency could upregulate IGFBP2 expression level as well as attenuate sensitivity to MAPKi, and thereby enhancing BRAFV600E melanoma cell survival via triggering IGF-1R/AKT signaling pathway." (PMID 33768092, 2021). "Inspired by the work of Dong and colleagues, which demonstrated that FOXO3a could be enriched in the Sirt6 promoter region and promote its transcription in the MV3 melanoma cell line, we hypothesized that Sirt6 regulation during the EMT in HK2 cells is associated with FOXO3a." (PMID 34122724, 2021). "Therefore, we could consider complete SIRT6 depletion (e.g., CRISPR) as a potential novel strategy to enhance melanoma cell sensitivity to current targeted MAPKi therapies." (PMID 30143629, 2018).